PSORS1C3 (psoriasis susceptibility 1 candidate 3)
Synonyms: NCRNA00196
Gene: Long non-coding RNA gene on chromosome 6 (31,173,735 to 31,186,118, reverse strand). Ensembl gene ENSG00000204528.
Diseases named in the same sentence as PSORS1C3 in open-access papers:
PSORS1C3 is named in the same sentence as 8 diseases in open-access papers, as found by Europe PMC text mining. Sharing a sentence is not in itself a finding about the gene and the disease. The quoted sentences say what the papers report.
psoriasis (6 papers, 2018 to 2025). An autoimmune condition characterized by red, well-delineated plaques with silvery scales that are usually on the extensor surfaces and scalp. "A relatively new psoriasis susceptibility gene, PSORS1C3 (psoriasis susceptibility 1 candidate 3), that lies close to genes involved in immune system regulation has surfaced in the literature with connections to MDD and suicide." (PMID 37174656, 2023). "For example, psoriasis susceptibility 1 candidate 3 (PSORS1C3) is mostly reported in psoriasis-related studies, hence its name." (PMID 35907897, 2022). "Our database search revealed that research on PSORS1C3, as its name suggests, primarily focuses on its involvement in psoriasis, while studies on HLA‐DRB6 have stagnated since the 1990s." (PMID 40099350, 2025).
autoimmune disease (3 papers, 2023 to 2024). A disorder resulting from loss of function or tissue destruction of an organ or multiple organs, arising from humoral or cellular immune responses of the individual to their own tissue constituents. "In our results, we also find a variety of pseudogenes (HLA-DRB6, CYP21A1P, PSORS1C3) that have a significant effect on the risk of autoimmune diseases." (PMID 39590325, 2024).
breast carcinoma (1 paper, 2019). "After survival analysis and ROC curve analysis of each DERNA, eight lncRNAs (AC104472.1, PSORS1C3, DSCR9, OSTN-AS1, AC012074.1, AC005035.1, SIAH2-AS1, and ERVMER61-1) and one mRNA, SPOPL, were identified as prognostic factors in breast cancer." (PMID 31572452, 2019).
congenital lung malformations (1 paper, 2021). "Subsequently, we highlighted two DE lncRNAs FLJ26850 and PSORS1C3, both of which interacted with miRNA processing complexes and were typically upregulated in congenital lung malformations." (PMID 34844556, 2021).
skin disorder (1 paper, 2023). Any deviation from the normal structure or function of the skin or subcutaneous tissue that is manifested by a characteristic set of symptoms and signs. "Similarly, other genes linked to skin disorders include PSORS1C3 (spring-born), and LTB4R (winter-born), both of which are known to be linked to the autoimmune disease psoriasis." (PMID 37697338, 2023).
PSORS1C3 also shares sentences with these, for which no sentence is quoted: ankylosing spondylitis (1 paper); major depressive disorder (1); rheumatoid arthritis (1).